INS (insulin)
Diseases named in the same sentence as INS in open-access papers (continued):
Sharing a sentence is not in itself a finding about the gene and the disease.
cancer (continued). "The crude incidence rate assessed for all cancer sites was higher in users of ADM, being highest in insulin users." (PMID 25419576, 2014). "Cetuximab, a humanized anti-EGF receptor monoclonal antibody used for the treatment of cancer, completely inhibited EGF-induced BRET, and the tyrosine kinase inhibitor tyrphostine AG1024 inhibited insulin effect on PIP3 production." (PMID 24647478, 2014). "Therefore insulin glargine and human insulin may have different effects on cancer development." (PMID 24466131, 2014). "The statistical analysis compared the rates of cancer in new glargine vs. new NPH users while on treatment, adjusted for the propensity to receive one or the other insulin." (PMID 25329887, 2014). "The increase in insulin and IGF-1 are considered mitogenic factors contributory to cancer development." (PMID 24308813, 2013). "Over-expression of IR-A was suggested to contribute to the modulation of insulin and IGF responses in different tissues and during cancer progression." (PMID 23805988, 2013). "However, whether this increased risk is related to a deleterious effect of sulfonylurea and insulin or a protective effect of metformin or due to some unmeasured effect related to both choice of therapy and cancer risk is not known." (PMID 23415113, 2013). "Stimulation with insulin and IGF-I in MDA-MD-435 cancer cells overexpressing E-cadherin induces a decrease of bisecting GlcNAc N-glycans that was accompanied with alterations on E-cadherin cellular localization." (PMID 24282611, 2013). "Therefore, the insulin/IGF receptors could serve as potential targets in AKT-dependent cancers." (PMID 24151577, 2013). "The potential link between the insulin/IGF-I signaling pathways and cancer has been the focus of much investigation over the last several years." (PMID 23620761, 2013). "The parameters k30f, k30r and k35f were varied to fit the timecourse of Insulin-stimulated PTP deactivation in 3T3-L1 cells and reactivation in human A431 carcinoma cells." (PMID 23705851, 2013). "Several clinical trials using IL-7 are currently underway in cancer, HIV, HBV and HCV infections to remediate disease-associated immune deficits and our results in mice suggest that increasing IL-7 levels may also affect fat mass development and insulin sensitivity in the IL-7-treated patients." (PMID 22768283, 2012). "Androgen exposure upregulated pathways related to insulin, mTOR and peroxisome proliferator-activated receptor (PPAR) signaling, and downregulated those involved with the cell cycle, RNA transport and cancer." (PMID 22605918, 2012). "Nevertheless, the intersection between mTOR, insulin signaling, and AMPK provides an intriguing, tantalising link between cellular energy and cancer pathways." (PMID 22548055, 2012). "In other words, overexpression of IR serves as a major mechanism of IGF1R signaling in cancer cells by enabling the formation of more heterodimers which are available for binding ligands including IGF1, IGF2, and insulin." (PMID 22438913, 2012). "Metformin negatively regulates mammalian target of rapamycin (mTOR) complex 1 (mTORC1) and the crosstalk between insulin/IGF-1 receptor and G-protein coupled receptor (GPCR) signaling, thus inhabiting the development of certain types of cancer." (PMID 22920886, 2012). "Emphasis will be placed on the role of insulin and IGF1 signaling in tumorigenesis as well as altered dietary needs of cancer patients." (PMID 22029671, 2011). "Also, insulin or insulin like growth factor levels may promote cancer cell and tumor growth." (PMID 22205924, 2011). "The direct, insulin-independent effects of metformin originate from LKB1-mediated activation of AMPK and a reduction in mTOR signaling and protein synthesis in cancer cells." (PMID 21470407, 2011).
cancer (continued). "Third, high plasma glucose concentrations elevate the levels of circulating insulin and free IGF1, two potent anti-apoptotic and growth factors for most cancer cells." (PMID 22029671, 2011). "Evidence exists that chronically elevated blood glucose, insulin and IGF1 levels facilitate tumorigenesis and worsen the outcome in cancer patients." (PMID 22029671, 2011). "Also Rudolf Kaaks showed a follow-up of his earlier epidemiologic data, now focusing on the impact of insulin on sex hormones and SHBG (sexual hormone binding globulin), which might explain some of the association between obesity and cancer incidence and proliferation." (PMID 21176129, 2010). "Low HDL-C is further related to increased levels of several other hormones including estrogens, insulin, and IGF-I, all of which can stimulate cancer development." (PMID 24281091, 2010). "Dysfunctional WAT, present under obese conditions, leads to systemic changes that can impact cancer progression by inducing modifications in the circulating levels of WAT‐derived factors and insulin signaling, altering systemic lipid metabolism and triggering an inflammatory state." (PMID 39496581, 2025). "IGF-1, along with insulin, activates the PI3K/AKT/mTOR pathway, promoting cell growth, proliferation, and survival while inhibiting apoptosis, which are key processes that support cancer cell development." (PMID 40566597, 2025). "The insulin/IGF axis, which includes insulin resistance, high insulin levels, and IGF, along with high blood glucose, inflammatory cytokines, and sex hormones, collectively create a favorable environment for cancer cell." (PMID 41164182, 2025). "IR-A is primarily expressed in fetal tissues and the brain, exhibits a greater affinity for both insulin and IGF-2, demonstrates a higher internalization rate than the type-B isoform, and is often up-regulated in cancer, while IR-B expression is most pronounced in the liver." (PMID 40141412, 2025). "This review found that KD results in improved cancer-related fat mass, visceral fat mass, LDL cholesterol, total cholesterol, β-hydroxybutyrate, thyroid-stimulating hormone, insulin, blood glucose, emotional function, fatigue, insomnia, social function, and ketosis events." (PMID 40756563, 2025). "By regulating insulin signaling, drugs such as MTX also alleviate metabolic disturbances, improving immune homeostasis and thereby enhancing the effectiveness of established cancer treatments." (PMID 41178737, 2025). "This enhanced capacity for glucose uptake supplies cancer cell dependence on aerobic fermentation to facilitate their bioenergetic needs via cytosolic substrate-level phosphorylation, independent of insulin mediated glucose uptake signalling." (PMID 41586225, 2025). "We found that most cancer cell lines co-cultured with CRISPRa-AAV-treated adipocytes showed a significant reduction in both basal and maximal glycolytic rate and lower glucose uptake in both basal and insulin conditions." (PMID 39905264, 2025). "It is hypothesized that a FMD may promote cancer prevention in mouse models by reducing levels of IGF-1, insulin, leptin, glucose, visceral fat, and other disease and aging markers." (PMID 39940361, 2025). "The association of insulin and insulin-like growth factor I levels, generally not monitored in these studies, with a gradual rise in IR, may lead to cellular proliferation and reduced apoptosis, potentially contributing to both atheromatosis and potentially to cancer." (PMID 39806381, 2025). "The most common cause of DKA in the general population is insulin nonadherence, but limited data exists on precipitating factors for DKA in cancer patients." (PMID 40940823, 2025). "Additionally, cancer‐related inflammation, characterized by elevated cytokines such as TNF‐α and IL‐6, further disrupts insulin signaling, exacerbating metabolic dysfunction." (PMID 40195579, 2025).
cancer (continued). "Insulin and estrogen signaling may synergically stimulate cell proliferation through activation of RAS/MAPK and PI3K/AKT pathways in different types of cancer cells." (PMID 40374694, 2025). "Some studies document reductions in fasting insulin levels with GLP-1R therapy in cancer settings; however, insulin levels are not always reported." (PMID 41178720, 2025). "Furthermore, emerging evidence suggests that MTF's effects on insulin and IGF‐1 signaling extend beyond cancer cells to impact the tumor microenvironment." (PMID 39969135, 2025). "MTF's modulation of insulin and IGF‐1 signaling may influence the interactions between cancer cells and surrounding stromal cells, immune cells, and blood vessels within the tumor microenvironment." (PMID 39969135, 2025). "Conversely, the promotion of insulin secretion by GLP-1 agonists could, in certain contexts, stimulate tumor growth, particularly in cancers sensitive to insulin and insulin-like growth factors." (PMID 39777709, 2025). "For cancer, the top 10 factors were age, TYG, TG, insulin, LDL‐c, AIP, BUN, Cr, TYG_BMI, and RAR." (PMID 40874812, 2025). "In terms of anti-cancer mechanisms, metformin can directly inhibit the malignant characteristics of cancer cells through activating AMPK signaling, or indirectly prevent tumorigenesis through controlling circulating glucose and insulin levels." (PMID 39135791, 2024). "Thus, limiting dietary protein would potentially lower the growth factors involved in glucose metabolism (i.e., insulin and IGF), impair cancer growth, and sensitize tumors with anti-cancer therapies, such as PI3K inhibitors." (PMID 39702320, 2024). "In that case, insulin is a key driver for both T2DM and cancer." (PMID 38392069, 2024). "The upregulation of IR-A enhances the mitogenic response of cancer cells to insulin and IGF-2, indicating that these isoforms could serve as potential targets for anti-cancer therapies." (PMID 38731097, 2024). "In a Mendelian randomization study, fasting insulin was associated with an increased risk of CRC, but not of other cancers." (PMID 39103728, 2024). "SGLT2Is are also thought to enhance insulin sensitivity and diminish chronic inflammation, which may help mitigate the inflammatory microenvironment in T2DM that facilitates cancer development." (PMID 38856768, 2024). "Nevertheless, our results show that exercise influences insulin resistance in some cancer patients and with some protocols, but generalizing is not possible." (PMID 38339407, 2024). "The insulin/insulin-like growth factor (IGF) signalling pathway to mTOR is essential for the survival and growth of normal cells and also contributes to the formation and progression of cancer." (PMID 39558974, 2024). "In mouse models, the FMD synergistically improved the cancer-fighting impact of endocrine therapies, such as tamoxifen and fulvestrant, by significantly lowering systemic levels of IGF-1, insulin, and leptin, and impeding AKT–mTOR signaling pathways through the increased expression of EGR1 and PTEN." (PMID 38321992, 2024). "As the IGF and insulin signaling axes have a crucial role in EAC cell proliferation and cancer progression, targeting IGF-IR/IR might therefore be an encouraging anticancer therapeutic path for EAC." (PMID 39335147, 2024). "(E) SKM contractile activity-induced decreases in IGF-1, IGFBP-2, and insulin levels and increased IGFBP-1 and -3 levels may also help to limit cancer development in SKM." (PMID 38928185, 2024). "Recent study conducted has shown that mTORC2 inhibition holds potential in cancer treatment but may have adverse effects on insulin sensitivity; however, combining mTORC2 inhibitors with AMPK activators could enhance their anti-cancer effects." (PMID 39201332, 2024).
cancer (continued). "The activation of IGF-1R by insulin triggers several signaling pathway, including PI3K/AKT, MAPK, JAK/STAT, Sarcoma (Src), and focal adhesion kinase (FAK), all of which collectively enhance cancer cell proliferation, survival, and migration." (PMID 39290325, 2024). "Our data suggest that different cancer cell lines exhibit differences in cellular uptake of exogenous ARG when cells were treated with both ARG and insulin simultaneously, which did not appear to be associated with the level of insulin receptor expression." (PMID 38374190, 2024). "CR and, in particular, insulin/IGF1 inhibition slows down the cell cycle and thus global tumor growth, but at the same time attenuates responsiveness to innate immune pathways that would induce cancer stem-cell clearance, favoring their persistence." (PMID 38280853, 2024). "Nonetheless, the ketogenic diet has been shown to limit cancer growth in many preclinical models via lowering of insulin and IGF-1, and intriguingly has shown synergy in combination with cancer therapies that disrupt the insulin/IGF-1/PI3K axis in host organs." (PMID 38873602, 2024). "Clinical trials in various cancer patients have failed, with monoclonal antibodies targeting only IGF-1R without IR due to the advancement of tumor growth, most likely arising from the escape mechanism involving insulin." (PMID 39335147, 2024). "From our study we concluded that although insulin plays a role in protein metabolism, cell survival and proliferation, it does not provide cancer cells with any survival advantage in vitro under arginine starvation conditions." (PMID 38374190, 2024). "In vitro, at least, these findings imply that insulin does not offer a growth or survival benefit to cancer cells being treated with ARG." (PMID 38374190, 2024). "High levels of insulin found in diabetic patients can also activate the IGF1 receptor and this may contribute to cancer cell growth." (PMID 38920688, 2024). "Regarding resistance exercise, no studies using animal models of cancer were found evaluating insulin sensitivity." (PMID 39062775, 2024). "Neither insulin treatment nor PST treatment alone were sufficient for induction of total cellular ROS production in the adipocyte-like cancer cell line 3T3-L1." (PMID 38397817, 2024). "The insulin-gastrin (InsGAS FVB/N-Tg(Ins1-GAS)1Sbr/J) hypergastrinemia mouse model is an excellent model of carcinogenesis; in response to H. pylori infection, these mice develop metaplasia, dysplasia, and carcinoma (originally reported)." (PMID 39588838, 2024). "Metformin can exert direct effects on cancer cells independent of blood glucose and insulin levels, partly through AMPK activation." (PMID 37344841, 2023). "Numerous studies suggest that the overactivation of the IR-A pathway, induced by insulin and IGF-2, plays a direct and crucial role in cancer development and may contribute to resistance against various anti-cancer drugs." (PMID 37834454, 2023). "The 4 main signaling pathways previously implied to be linked to the impact of CR on life span, the insulin/ IGF-1, NF-ĸB, mTOR, and SIRT signaling pathways, showed no significant changes with the increase in CR level, neither did the pathways in cancer." (PMID 36757838, 2023). "PLD3 is related to insulin-mediated phosphorylation of the AKT pathway, suggesting that it may play a role in the occurrence and development of malignant tumors." (PMID 37978168, 2023).
cancer (continued). "Therefore, in this study, we also looked for changes in insulin/IGF-1, mTOR, NF-B, and Sirtuin signaling pathways, as well as signaling pathways related to cancer, in relation to the increase in the level of CR." (PMID 36757838, 2023). "Females had no change in insulin sensitivity or cancer rates, but showed a 15% increase in lifespan." (PMID 37881503, 2023). "High glucose levels in cancer patients increase the flux into HBP and improve GFAT enzyme levels, resulting in increased GFAT activity and inhibited glucose uptake and glycogen synthesis in insulin-resistant patients." (PMID 37415905, 2023). "The cancer risk of chronic intranasal IGF2 administration is likely to be low, as well; 1 year of daily intranasal administration of insulin, which is also a mitogenic peptide, did not increase cancer incidence in a large clinical trial." (PMID 36971212, 2023). "It has both a protective effect, where it plays a role in modulating immune function and improving insulin sensitivity, as well as a negative systemic effect, where it serves as a prognostic biomarker for cancer and cardiovascular disease." (PMID 37371414, 2023). "Insulin is a peptide hormone secreted by the pancreas that regulates glucose homeostasis, and high levels of circulating insulin can activate the PI3K-AKT-mTOR pathway which promotes growth in cancer cells." (PMID 37170094, 2023). "The GSVA revealed the biological features of CAFs, many cancer-related pathways, such as the adipocytokine signaling pathway, ERBB signaling pathway, GnRH signaling pathway, insulin signaling pathway, mTOR signaling pathway and PPAR signaling pathway are closely associated with CAFs." (PMID 36937411, 2023). "In fact, glucose and insulin deprivation occurring in patients undergoing a KDs promotes a metabolic environment, which is not suitable for cancer cells growth." (PMID 37405618, 2023). "As PTCL has several subtypes, upregulation of microRNA miR-187 reported across PTCL subtypes is known to decrease glucose-stimulated insulin secretion (GSIS) in metabolic syndromes; however, its role in cancer metabolic reprogramming is unknown." (PMID 37637043, 2023). "While normal cells depend on the insulin-IR interaction for enhanced uptake and utilization of glucose, these cancer cells did not utilize IR for enhanced glycolysis." (PMID 37373357, 2023). "The influence of the insulin/insulin-like growth factor (IGF) system on cell growth and proliferation plays a critical role in the acquisition of a malignant phenotype and the progression of several cancer cells." (PMID 37626857, 2023). "Vice versa, metabolic changes in the heart are unlikely to cause cancer development, but well-described metabolic repercussions of CVD, such as insulin insensitivity and diabetes, are clearly associated with an increased risk for cancer." (PMID 36004495, 2023). "Insulin and IGF-1 receptors can be observed in most types of cancer tissue." (PMID 38152132, 2023). "There is a lack of definitive information on the role of insulin in cancer, and the situation is made more complex by the existence of two insulin receptor isoforms, IR-A and IR-B." (PMID 36975518, 2023). "Evaluation studies show new insights concerning Ras/MAPK hyperactivation as a shared pathway, promising endocrine and homeostatic approaches, such as energy homeostasis (e.g. by leptin and insulin), calcium homeostasis and future treatments from the field of RAS-driven cancers." (PMID 37480127, 2023). "However, the role of IGF2 in cancer progression is certainly less characterized when compared to IGF1 and insulin." (PMID 36672737, 2023). "Increased circulating amounts of estrogen and/or insulin and IGF-1 may be one mechanism by which excess body fat promotes cancer development and progression in postmenopausal women (insulin-like growth factor)." (PMID 37049508, 2023). "The results showed that cancer incidence was higher among diabetic patients using insulin versus non-users." (PMID 38146457, 2023).